PCOLCE2 (procollagen C-endopeptidase enhancer 2)
Diseases named in the same sentence as PCOLCE2 in open-access papers:
PCOLCE2 is named in the same sentence as 41 diseases in open-access papers, as found by Europe PMC text mining. Sharing a sentence is not in itself a finding about the gene and the disease. The quoted sentences say what the papers report.
ovarian carcinoma (6 papers, 2016 to 2024). A malignant neoplasm originating from the surface ovarian epithelium. "However, upregulation of ECM remodeling genes (COL family genes, LUM, PCOLCE2) was selectively observed only in ovarian cancer TAMs." (PMID 33194645, 2020). "Importantly, PCOLCE2 protein was detectable at appreciable levels in the ascites of ovarian cancer patients." (PMID 27659538, 2016). "Finally, we also found readily detectable levels of PCOLCE2 protein by ELSIA in ovarian cancer ascites, supporting a potential functional relevance of the upregulated ECM signature genes." (PMID 27659538, 2016). "Several adverse clinical markers are highly expressed by ovarian cancer TAMs, including CD163, Procollagen C-endopeptidase enhancer 2 (PCOLCE2), IL-6 and IL-10." (PMID 32774171, 2020).
breast carcinoma (5 papers, 2010 to 2023). "The genes namely COL11A1, MMP11 and COL10A1 were found up regulated and PCOLCE2, LAMA2, TMTC1, ADAMTS5, TIMP4 and RSPO3 were found down regulated in breast cancer." (PMID 37238942, 2023). "In conclusion, our study identified nine key regulators, of which COL11A1, MMP11 and COL10A1 were up regulated and PCOLCE2, LAMA2, TMTC1, ADAMTS5, TIMP4 and RSPO3 were down regulated in breast cancer samples as compared to control samples." (PMID 37238942, 2023). "The genes namely COL11A1, MMP11 and COL10A1 were found up-regulated and PCOLCE2, LAMA2, TMTC1, and TIMP4 were found down-regulated in breast cancer cell lines also." (PMID 37238942, 2023). "Among these key genes COL11A1, MMP11 and COL10A1 were highly expressed and PCOLCE2, LAMA2, TMTC1, ADAMTS5, TIMP4, and RSPO3 were having lower expression levels in breast cancer samples." (PMID 37238942, 2023). "Importantly, increases in COL8A1, BGN, COL11A1, POSTN, MMP11 and SORCS2 and decreased LTBP4, PCOLCE2, LRRC17 and SDK1 have been identified in CAS and CAFs from human breast cancer and are consistently perturbed in stroma of canine and human mammary cancer." (PMID 37391533, 2023). "Similarly, for early breast cancer, the best three k-gene discriminators are {GPR109B, PCOLCE2, PCSK5}, {PCSK5+COL10A1, FERMT2+SPINT2, MAOA+IGJ}, {COL1A1+PCSK5+TF, GPX3+COL1A1+SPINT2, GPX3+FAP+TMEM97}, and {RRM2+COL1A1+GPR109B+IGJ, RRM2+COL1A1+GPR109B+IGJ, RRM2+COL1A1+GPR109B+SPINT2}, respectively." (PMID 21060876, 2010).
colorectal cancer (5 papers, 2021 to 2024). A primary or metastatic malignant neoplasm that affects the colon or rectum. "Research has identified PCOLCE2 as a novel gene signature for high-risk groups in age-stratified analyses of colorectal cancer patients." (PMID 39374805, 2024). "PCOLCE2 has been implicated in the colorectal cancer and gastric cancer, however, the expression pattern of PCOLCE2 is poorly understood." (PMID 37238942, 2023). "PCOLCE2 is reported to encode a functional collagen-binding protein procollagen C-proteinase enhancer (PCPE2), and evidence has proved that PCOLCE2 was able to perform as a biomarker for prognostic prediction in colorectal cancer patients." (PMID 36590308, 2022). "DLX2 and PCOLCE2 are potential tumor markers of early-onset colorectal cancer." (PMID 34789836, 2021). "The high expression of DLX2 and PCOLCE2 may influence and participate in the occurrence of colorectal cancer, and lead to the occurrence of early-onset colorectal cancer." (PMID 34789836, 2021). "Additionally, PCOLCE2 was among nine key prognostic genes reported in colon adenocarcinoma and was included in a prognostic gene group of nine in integrated bioinformatics analyses of colorectal cancer." (PMID 39374805, 2024).
gastric cancer (5 papers, 2021 to 2023). A primary or metastatic malignant neoplasm involving the stomach. "PCOLCE2 can be considered as an EMT-linked gene for anticipating the prognosis of gastric cancer patients and the metastasis ability of COAD." (PMID 37350934, 2023). "Nevertheless, more research should be conducted for investigating the roles of PCOLCE2 in gastric cancer progression." (PMID 34746312, 2021). "PCOLCE2 has been demonstrated to be a prognostically relevant biomarker for CRC, gastric cancer, bladder cancer, head and neck squamous cell carcinoma, and thyroid cancer." (PMID 36910014, 2023). "Here, we developed an EMT-related RS model that was comprised of SERPINE1, PCOLCE2, MATN3, and DKK1 in gastric cancer via the LASSO method, which may classify gastric cancer patients into the high- and low-risk categories." (PMID 34746312, 2021).
Sepsis (4 papers, 2019 to 2024). Sepsis is defined as life-threatening organ dysfunction caused by a dysregulated host response to infection. "In addition, there was association with FGF13 through BST1 and PCOLCE2 through SH3GLB1 in pediatric sepsis." (PMID 32318053, 2020). "A meta-analysis using artificial neural networks on SIRS/sepsis and other infection datasets identified eight core hub genes, including PCOLCE2, associated with SIRS/sepsis immunopathology." (PMID 39374805, 2024). "In pediatric sepsis there are again alterations in the complement of genes associated with each hub gene and significantly increased stimulatory interactions for nearly all hubs, with the exception of KLRK1 and PCOLCE2." (PMID 32318053, 2020). "The majority of these clusters were not connected in most disease and control states, except for adult sepsis and adult SIRS with the gene clusters for TDRD9, CD177, GPR84, PCOLCE2, FGF13 and SLC16A3 interconnected at various points, either directly or through overlapped gene connections." (PMID 32318053, 2020). "CD177, ARG1, FAM20A, PCOLCE2, SLC51A, MMP9, were identified as most significantly upregulated in both SIRS and Sepsis on Day1, compared with healthy controls, with CD177 and ARG1 consistently higher for both SIRS and Sepsis at this and across all timepoints to discharge." (PMID 38332914, 2023).
rectal cancer (3 papers, 2021 to 2023). A primary or metastatic malignant neoplasm that affects the rectum. "Previous study reported mutations in PCOLCE2 in patients with rectal cancer, but the specific mechanism of PCOLCE2 in CRC is less known." (PMID 34789836, 2021). "In a previous study, patients with rectal cancer were found to have mutations in PCOLCE2." (PMID 38054820, 2023).
thyroid cancer (3 papers, 2022 to 2023). "Kaplan–Meier plots suggested that high expression of PCOLCE2 and HTRA3 were associated with poor prognostic outcomes of thyroid cancer patients in TCGA." (PMID 36387901, 2022). "Here, we performed LASSO analysis and identified 6 critical fibroblasts related factors (PCOLCE2, APOD, APOE, TIMP1, HTRA3 and MT1A) and calculated the fibrosis scores based on their expression in patients with thyroid cancer." (PMID 36387901, 2022). "Secondly, the expression of PCOLCE2 and HTRA3 were decreased in thyroid tumor and indicated favorable prognosis for thyroid cancer patients, which is contradictory to the conventional perception." (PMID 36387901, 2022). "Survival analysis suggested that high expression level of PCOLCE2 and HTRA3 were related to poor overall survival results for thyroid cancer patients." (PMID 36387901, 2022). "Here, we showed that PCOLCE2 and HTRA3 were mainly expressed by fibroblasts in thyroid cancer and decreased in tumor tissues." (PMID 36387901, 2022). "However, low expression of PCOLCE2 and HTRA3 suggested favorable clinical outcomes for thyroid cancer patients." (PMID 36387901, 2022). "It is our study that collects LRRN4CL, HS3ST3A1, PCOLCE2, and CAPN8 all together for the first time and sets them as biomarkers related to TME in thyroid cancer, which might become potential candidate targets for TC immunotherapy." (PMID 36590308, 2022).
atherosclerosis (2 papers, 2018 to 2024). A disease characterized by the build-up of fatty material and calcium deposition in the arterial wall resulting in partial or complete occlusion of the arterial lumen. "Recent biological evidence suggests strong causal links between PCOLCE2 activity and atherosclerosis, while a series of recent articles are beginning to tease out the phospholipid related functionality of LPCAT3." (PMID 29652918, 2018). "The Pcolce2 knockout yielded a phenotype like that reported for Scarb1-KO mice, which also exhibit increased atherosclerosis despite elevated plasma HDL levels." (PMID 39374805, 2024).
influenza (2 papers, 2024). An acute viral infection of the respiratory tract, occurring in isolated cases, in epidemics, or in pandemics; it is caused by serologically different strains of viruses (influenzaviruses) designated A, B, and C, has a 3-day incubation period, and usually lasts for 3 to 10 days. "As noted in other studies, the role PCOLCE2 plays in severe influenza immune response remains unknown." (PMID 39374805, 2024). "Functional studies showed that, unlike HLA DPA1, PCOLCE2 levels were significantly higher in the severe influenza group compared to the non-severe influenza group." (PMID 39374805, 2024). "The ten common DEGs (PCOLCE2, HLA_DPA1, LOC653061, TDRD9, MPO, HLA_DQA1, MAOA, S100P, RAP1GAP, and CA1) that were obtained by overlapping genes from computing the three algorithms [LASSO regression, SVM-RFE algorithms, and RF are candidate key genes for severe influenza." (PMID 38454348, 2024). "In contrast, PCOLCE2, TDRD9, MPO, MAOA, RAP1GAP, and S100P expression was higher in the severe influenza group compared to the non-severe influenza group in the training cohort, similar to the findings in the validation cohort." (PMID 38454348, 2024).
lung carcinoma (2 papers, 2025). "In addition to MMP‐14, other ECM digestive regulators, such as Procollagen C‐Endopeptidase Enhancer 2 (PCOLCE2), a predictive marker for epithelial‐to‐mesenchymal transition and metastasis in lung cancer, were also observed with elevated synthesis levels in dECM‐tumors." (PMID 40913457, 2025). "In addition to MMP-14, other ECM regulators, such as Procollagen C-Endopeptidase Enhancer 2 (PCOLCE2), a predictive marker for epithelial-to-mesenchymal transition and metastasis in lung cancer, were also observed with elevated synthesis levels in the dECM-tumors." (PMID 40166338, 2025).
type 2 diabetes (2 papers, 2022 to 2024). "Single-cell RNA sequencing studies have shown that pancreatic islet cells from type 2 diabetes patients exhibit high levels of PCOLCE2 mRNA along with several other genes." (PMID 39374805, 2024). "MiR-192-5p appears to be involved in type 2 diabetes (T2DM) by regulating the expression of several genes involved in T2DM, such as procollagen C-endopeptidase enhancer 2 (PCOLCE2), which is significantly decreased in T2DM." (PMID 35613088, 2022).
colon adenocarcinoma (1 paper, 2024). "Furthermore, a ferroptosis-related gene signature associated with invasion and metastasis in colon adenocarcinoma identified PCOLCE2 as one of four key prognostic genes." (PMID 39374805, 2024).
colon cancer (1 paper, 2021). "We identified seven EMT-related genes (TPM1, LAMC1, POSTN, CCN1, MGP, PCOLCE2, and DPYSL3) with prognostic significance in patients with colon cancer from TCGA and GSE17536 cohorts." (PMID 34180352, 2021).
colorectal adenocarcinoma (1 paper, 2019). The most common type of colorectal carcinoma. "S100A4, but not MYLK, BDNF, and PCOLCE2, exhibited higher expression in colorectal adenocarcinoma, but lower expression in normal colon tissues." (PMID 31581665, 2019).
deafness (1 paper, 2024). An inherited or acquired condition characterized by the complete loss of the ability to hear from one or both ears. "AAV‐mediated gene therapy, which combines Pcolce2 with multiple signalling pathways, is expected to be a new therapeutic strategy for deafness in the clinic." (PMID 38528645, 2024).
depression (1 paper, 2022). "PCOLCE2 is highly expressed in the pituitary and there is evidence of reduced levels in depression-like behaviours in mice, consistent with rs9757063 effect." (PMID 36276939, 2022).
Dupuytren’s disease (1 paper, 2016). "We have found that nodule is the more pro-fibrotic tissue in Dupuytren’s disease, characterized by an RNA profile consistent with fibrogenesis, but with lower levels of actual collagen I deposition, possibly caused by an abnormal collagen biosynthesis, as evidenced by a lower expression of PCOLCE2." (PMID 27366208, 2016).
endometrial cancer (1 paper, 2021). Primary or metastatic malignant neoplasm involving the endometrium (mucous membrane that lines the endometrial cavity). "Recent studies found PCOLCE2 has been identified as the central gene of endometrial cancer progression, and low expression of PCOLCE2 is associated with longer overall survival duration which is consistent with our findings." (PMID 34789836, 2021).
glioma (1 paper, 2022). A benign or malignant brain and spinal cord tumor that arises from glial cells (astrocytes, oligodendrocytes, ependymal cells). "Among them, PCOLCE2, ERP27, PSMD13, C14orf39, C16orf86, UGCG, and HPX were identified as prognostic factors for glioma for the first time." (PMID 35873494, 2022).
mucopolysaccharidoses (1 paper, 2024). "In mucopolysaccharidoses (MPS), a group of lysosomal storage diseases associated with neurodegeneration, PCOLCE2 along with three other genes, was found to be up-regulated across all MPS types and subtypes." (PMID 39374805, 2024).
Myocardial fibrosis (1 paper, 2023). "Only 1 of the 3 upregulated genes in this category, PCOLCE2, has any evidence that its encoded protein can participate in myocardial fibrosis enhancement." (PMID 37606047, 2023).
osteoarthritis (1 paper, 2019). A noninflammatory degenerative joint disease occurring chiefly in older persons, characterized by degeneration of the articular cartilage, hypertrophy of bone at the margins and changes in the synovial membrane. "Several other non-structural components with important cartilage ECM roles in development or osteoarthritis were also downregulated, including proteoglycan-related gene 4/lubricin (Prg4), procollagen C-endopeptidase enhancer 2 (Pcolce2), and Cytokine-like 1 (Cytl1)." (PMID 30793021, 2019).
scleroderma (1 paper, 2023). Scleroderma is a rare autoimmune connective tissue disorder characterized by abnormal hardening of the skin and, sometimes, other organs. "In the skin, this transcriptional signature was observed in fibroblasts from unwounded skin responsible for ECM homeostasis and in a fibroblast population that undergoes contraction in scleroderma as compared to healthy skin (PI16+MFAP5+PCOLCE2+)." (PMID 37277655, 2023).
tumor (11 papers, 2020 to 2024). "We verified that LEP, NGF and PCOLCE2 were highly expressed in tumor tissues using COAD clinical samples." (PMID 38694509, 2024). "In thyroid cancer studies, PCOLCE2 was found to be one of four tumor microenvironment-related genes significantly affecting prognosis." (PMID 39374805, 2024). "The expression levels of LEP, NGF and PCOLCE2 proteins in tumor tissues were significantly increased compared with adjacent tissues." (PMID 38694509, 2024). "PCOLCE2 is a collagen-binding protein that functions as a pivotal component in tumor microenvironment remodeling, and a previous study also demonstrated that down-regulation of PCOLCE2 expression resulted in better OS." (PMID 36973787, 2023). "The high expression of LEP, NGF and PCOLCE2 in tumor tissues was verified by COAD clinical samples." (PMID 38694509, 2024). "Besides, PCOLCE2 was identified as a key factor in tumor epithelial-mesenchymal transition (EMT) and ferroptosis." (PMID 36387901, 2022). "We validated the transcriptional expression of identified 6 key fibrosis factors (PCOLCE2, APOD, APOE, TIMP1, HTRA3 and MT1A) in tumor and normal tissues obtained from 20 PTC patients." (PMID 36387901, 2022). "We also found that ARL4C and HOXC8 were upregulated, and FABP4, PCOLCE2, SERPING1, and SRPX were downregulated in tumor tissue compared to corresponding healthy tissue." (PMID 35664768, 2022). "Collectively, these studies implicate PCOLCE2 expression in colorectal adenocarcinoma and suggest that its involvement in ECM receptor interactions and the Wnt signaling pathway may contribute to tumor growth and metastasis." (PMID 39374805, 2024). "The protein expression of PCOLCE2, APOD and TIMP1 displayed no significant changes in tumor and normal thyroid tissues." (PMID 36387901, 2022). "The results revealed that the expression level of PCOLCE2 and HOXC11 in COAD patients was significantly higher than that in healthy individuals, regardless of for M tumor stage, lymph node metastasis and peritoneal metastasis (p < 0.05)." (PMID 35155451, 2021). "The Wilcoxon rank-sum test indicated the expression levels of 4 DEGs among normal and tumor tissue in paired or unpaired samples, which indicated HS3ST3A1 and CAPN8 expressed significantly higher in tumor tissues, while the other two genes, LRRN4CL and PCOLCE2, were not." (PMID 36590308, 2022).
cancer (7 papers, 2016 to 2025). A tumor composed of atypical neoplastic, often pleomorphic cells that invade other tissues. "Recently, sc-RNA sequencing studies have highlighted PCOLCE2’s role in various physiological and pathological processes, including inflammation and cancer." (PMID 39374805, 2024). "We also identified 5 genes (LGR4, RARG, PNISR, PCOLCE2, RALGDS) that shared the same patterns across three types of cancer, and 39 genes with two overlaps across eight cancer types." (PMID 32764426, 2020). "Given the documented connection between PCOLCE2, TGF-β, and BMP-1 activity upregulation of PCPE2 may significantly influence cancer progression through modulation of this pathway." (PMID 39374805, 2024). "In addition, higher S100A4 expression was observed in various cancer types compared to MYLK, BDNF, and PCOLCE2." (PMID 31581665, 2019). "The Pro-collagen C-endopeptidase enhancer (PCOLCE2), has no known relation to cancer." (PMID 26872740, 2016).
infection (2 papers, 2022 to 2024). The state of being infected such as from the introduction of a foreign agent such as serum, vaccine, antigenic substance or organism. "Transcriptomic profiling identified a module of 26 genes, including PCOLCE2, predictive of glycoprotein acetylation, inflammation, activated neutrophils, and infection risk." (PMID 39374805, 2024).
PCOLCE2 also shares sentences with these, for which no sentence is quoted: Arthritis (1 paper); bladder cancer (1); breast tumour (1); corneal dystrophies (1); emphysema (1); head and neck squamous cell carcinoma (1); hearing loss (1); leukemia (1); membranous nephropathy (1); myocardial infarction (1); myopathies (1); nasopharyngeal carcinoma (1); papillary carcinoma (1); thyroid tumor (1); uterine corpus endometrial carcinoma (1).